CDK5 (cyclin dependent kinase 5)
Diseases named in the same sentence as CDK5 in open-access papers (continued):
Sharing a sentence is not in itself a finding about the gene and the disease.
hepatocellular carcinoma (24 papers, 2010 to 2025). A malignant tumor that arises from hepatocytes. "In hepatocellular carcinoma, Cdk5 promotes the degradation of the immune checkpoint molecule PD-L1 through chaperone-mediated autophagy (CMA)." (PMID 41369365, 2025). "CDK5 deficiency in hepatocellular carcinoma (HCC) cells upregulates PD-L1 through decreased phosphorylation and reduced chaperone-mediated autophagy, enhancing response to anti-PD-1 immunotherapy and improving survival in HCC-bearing mice." (PMID 39315094, 2024). "Recent studies found that CDK5-mediated phosphorylation of TPX2 (Target protein for Xklp2) at Ser486 stabilizes TPX2 to promote the migration of hepatocellular carcinoma cells." (PMID 35006426, 2021). "Inhibition of Cdk5 activity by injection of roscovitine to mice bearing tumours derived from a hepatocellular carcinoma cell line resulted in decreased tumour vascularization." (PMID 31910742, 2020). "CDK5 was shown to phosphorylate ataxia telangiectasia mutated (ATM) protein at Ser729, thereby activating the DDR pathway in hepatocellular carcinoma cell lines." (PMID 31910742, 2020). "CDK5 has been demonstrated to stabilize HIF-1α in hepatocellular carcinoma, which is also one of the most vascularized tumors." (PMID 31311512, 2019). "Due to the oncogenic function of CDK5, Dinaciclib, an effective inhibitor of CDK5, exerted potent tumor-suppressing effect in relapsed multiple myeloma and hepatocellular carcinoma." (PMID 31496920, 2019). "Recently, several publications also reported high CDK5 expression levels in hepatocellular carcinoma." (PMID 29312535, 2017). "Inhibiting CDK5 activity in hepatocellular carcinoma (HCC) cells prevented angiogenesis in vivo by decreasing the abundance of HIF-1α." (PMID 28077789, 2017). "We first showed that p35, a critical regulatory protein for Cdk5, is expressed in the human liver carcinoma cell line HepG2." (PMID 20553580, 2010). "Lnc-ATG9B-4 prevents cell growth by upregulating CDK5 in hepatocellular carcinoma cells." (PMID 36635290, 2023). "One study using CRISPR/Cas9 technology to silence CDK5 clearly showed that knocking down CDK5 could potentiate the effects of sorafenib on attenuating the proliferation and survival of hepatocellular carcinoma cells." (PMID 35715750, 2022). "In addition, depletion or inhibition of CDK5 with roscovitine in hepatocellular carcinoma cell lines decreased expression of HIF-1α levels, and decreased expression levels of HIF-1α targets VEGFA, EphrinA1 in vivo and in vitro." (PMID 31910742, 2020). "The ablation of CDK5 suppresses angiogenic processes in hepatocellular carcinoma (HCC)." (PMID 33396266, 2020). "Indeed, Ehrlich and colleagues reported that CDK5 activity blockade in hepatocellular carcinoma cell lines prevented ATM phosphorylation and then blocked the initiation of the DNA damage response, including the G2/M arrest." (PMID 32708903, 2020). "Since CDK5 activity is vital for hepatocellular carcinoma tumorigenesis, drugs that target CDK5 kinase activity may be a potential curative treatment for HCC." (PMID 31272499, 2019). "Indeed, a more recent study showed that inhibiting CDK5 improved the sensitivity to Sorafenib-induced tumor suppression in xenografts of hepatocellular carcinoma cells." (PMID 30704449, 2019). "CDK5 regulates DNA damage response via phosphorylating Ataxia telangiectasia mutated (ATM) kinase and thereby affecting its downstream signal pathways which was crucial to progression of hepatocellular carcinoma." (PMID 26860827, 2016). "In hepatocellular carcinoma (HCC), for example, Cdk5 stabilization promotes metabolic reprogramming and cancer progression by modulating mitochondrial fission." (PMID 41369365, 2025). "Many malignant forms of cancer have been associated with elevated levels of CDK5, such as: medullary thyroid cancer (MTC), hepatocellular carcinoma (HCC)." (PMID 33805800, 2021).
hepatocellular carcinoma (continued). "Analyses of human hepatocellular carcinoma (HCC) tissue array revealed that overexpression of CDK5 correlates with higher vascular density." (PMID 31910742, 2020). "Recently, we have reported that CDK5 is highly expressed in hepatocellular carcinomas, and regulates DNA damage responses in HCC cells." (PMID 27027353, 2016). "CDK5 is introduced to stimulate the activity of targeting protein for Xklp2 (TPX2), leading to the migration of hepatocellular carcinoma cells." (PMID 33396266, 2020). "In hepatocellular carcinoma (HCC), CDK5 overexpression could promote proliferation of HCC cells to exert an oncogenic activity." (PMID 31496920, 2019). "Here we found that CDK5 and HIF1α can positively regulate DHHC7 expression and there is a positive feedback loop formed by DHHC7, STAT3, and HIF1α, which contributes to the malignancy of hepatic carcinoma." (PMID 38051779, 2023). "However, because flavonoids can inhibit Cdk5 and Cdk5/p35 signaling (which is not regulated by cell cycling) is active in hepatoma, we tested whether inhibition of Cdk5 by flavonoids is responsible for the flavonoids-mediated activation of PXR." (PMID 20553580, 2010). "However, the role and clinical significance of CDK5 and CKD5R1 (P35) in hepatocellular carcinoma have not been reported so far." (PMID 33346796, 2021).
colorectal cancer (23 papers, 2014 to 2025). A primary or metastatic malignant neoplasm that affects the colon or rectum. "CDK5 regulates cell cycle progression, cellular proliferation, and cell migration, and therefore, dysregulation of CDK5 in cellular functions can cause oncogenesis leading to lung and colorectal cancer." (PMID 32054125, 2020). "In colorectal cancer, high Cdk5 expression is associated with poor prognosis, and in gastric cancer, low Cdk5 expression has been associated with shorter patient survival." (PMID 32352232, 2020). "CDK5 has been implicated in a number of cancers, most recently as an oncogene in colorectal cancers." (PMID 29435174, 2018). "The importance of Cdk5-mediated talin phosphorylation is evident in colorectal cancer, where it promotes cancer progression and metastasis." (PMID 41369365, 2025). "Supporting this observation, previous research has demonstrated that Fusobacterium nucleatum promotes colorectal cancer progression through Cdk5-mediated activation of the WNT/β-catenin pathway." (PMID 40427657, 2025). "CDK5 and p35 are broadly expressed in human colorectal cancer (CRC) cell lines and human CRC tissues compared to paired normal tissues and cell lines." (PMID 37993880, 2023). "In the context of colorectal carcinoma, CDK5 represents an attractive target for treatment due to its high expression in tumor tissue, involvement in various aspects of oncogenesis, and potential to enhance the effects of DNA-damaging agents." (PMID 37511490, 2023). "This study examined the efficacy of selectively inhibiting CDK5 in colorectal carcinoma using TP5, a small peptide that selectively inhibits the aberrant and hyperactive CDK5/p25 complex while preserving physiological CDK5/p35 functions." (PMID 37511490, 2023). "High expressions of CDK5, p35, or p39 and hyper‐activation of CDK5 signaling have been reported in several cancers, including breast, ovarian, and colorectal cancer." (PMID 33960694, 2021). "CDK5, p35 and p39 have been found over-expressed in various tumours and high CDK5 levels correlate with poor prognosis in myeloma, breast, lung and colorectal cancers." (PMID 33924599, 2021). "In this study, we investigated the expression pattern of Cdk5 in colorectal cancer (CRC) cell lines and in a large number of tumor samples in order to evaluate its relevance in this pathogenesis and possible use as a prognostic marker." (PMID 31614664, 2019). "Having determined that 20-223 targets CDK2 and CDK5, we next examined the basal levels of these kinases in a cohort of colorectal cancer cell lines which includes seven CRC cell lines and one normal human colon epithelial cell line (HCEC)." (PMID 29435174, 2018). "Consequently, this up-regulation activates the expression of cyclin-dependent kinase 5 (Cdk5), thereby promoting the proliferation of colorectal cancer cells." (PMID 40510661, 2025). "In this study, we demonstrated that TP5 could reduce the activity of CDK5 in colorectal carcinoma (CRC) cells, leading to cell apoptosis." (PMID 37511490, 2023). "CDK5 participates in tumorigenesis via the ERK5-AP-1 signaling pathway, Inhibitors of CDK5 have proven effective for treating colorectal cancer." (PMID 35814446, 2022). "Abnormal expression of cyclin-dependent kinase 5 (CDK5) has been found in several human cancers, whereas the role of CDK5 in the malignant development of colorectal cancer (CRC) has not been well characterized." (PMID 27735944, 2016).
glioblastoma (23 papers, 2012 to 2025). The most malignant astrocytic tumor (WHO grade IV). "Consistent with a broad pro-proliferative role, Cdk5 knockdown in glioblastoma cells inhibits proliferation and induces apoptosis." (PMID 41369365, 2025). "OGT has been shown to regulate glioblastoma acetate metabolism by influencing cyclin-dependent kinase 5 (CDK5)-dependent ACSS2 phosphorylation." (PMID 39285476, 2024). "Its ability to respond to recombinant CDK5/p25 has been recognized and sensitive changes in fluorescence intensity report the CDK5 activity of glioblastoma cell extract." (PMID 37210528, 2023). "A biosensor for Cdk5 can be used to probe Cdk5 activity in living glioblastoma cells by fluorescence imaging." (PMID 35966199, 2022). "In U87 glioblastoma and Lewis lung cancer, inhibition of CDK5 can reduce VEGF expression to inhibit angiogenesis." (PMID 35006426, 2021). "Together, these findings confirm that DYRK1A negatively regulates SOX2 expression via CDK5 pathway and thus is necessary for the differentiation commitment of glioblastoma stem cells." (PMID 33924599, 2021). "Herein, we applied bioinformatics analysis to determine the clinical value of CDK5 in patients with glioma and examined the effects of CDK5 on glioblastoma cell proliferation, apoptosis, and cell cycle in vitro." (PMID 34093802, 2021). "In the present study, we showed that the use of TP5 was able to specifically decrease the activity of CDK5 in glioblastoma cells and induce cell apoptosis." (PMID 32708903, 2020). "CDK5 has also been reported to be highly expressed in glioblastoma possibly due to its location on chromosome 7, which is one of the most frequent sites of copy number increase in GBM." (PMID 32708903, 2020). "We examined the efficacy of selective inhibition of cyclin-dependent kinase 5 (CDK5) in glioblastoma by TP5." (PMID 32708903, 2020). "Taken together, CDK5 appears to be a very promising target in oncology, particularly for treating glioblastoma where irradiation and genotoxic agents are used as first line treatment." (PMID 32708903, 2020). "CDK5 is one of the early activated proteins after exposure to conventional DNA-damaging agents, which we also observed in glioblastoma cells." (PMID 32708903, 2020). "Phosphorylation of PIKE-A by CDK5 mediates growth factor-induced migration and invasion of human glioblastoma cells." (PMID 26146988, 2015). "Researchers have also found that CDK5 protein expression is related with apoptosis in human glioblastoma multiforme." (PMID 26205145, 2015). "Moreover, drugs targeting OGT and CDK5 have demonstrated efficacy in reducing glioblastoma tumors in vitro." (PMID 39285476, 2024). "TRIM59 is an E3 ligase and CDK5 substrate that mediates the CDK5 progression of glioblastoma." (PMID 38727267, 2024). "The implications of this innovation are far-reaching, as it promises to significantly enhance our understanding of CDK5 dynamics in glioblastomas and its role in disease progression, potentially leading to more effective diagnostic and therapeutic strategies for this challenging medical condition." (PMID 38139688, 2023). "Importantly, it equipped researchers with the means to explore the intricate signaling pathways at play within glioblastomas, shedding light on the potential hyperactivation of CDK5 and CDK4 in specific cell lines, like U87, or in tumor biopsies." (PMID 38139688, 2023). "Furthermore, DYRK1A mRNA expression negatively correlated (p < 0.005) with CDK5 mRNA expression in the TCGA glioblastoma dataset, which is in line with mechanistic data presented here." (PMID 33924599, 2021). "In glioblastoma, CDK5 expression was observed in 82.8% of WHO IV glioma." (PMID 35006426, 2021). "In addition, CDK5 inhibition improved efficacy of the standard-of-care therapeutics in glioblastoma, pancreatic and breast metastasis models." (PMID 33924599, 2021). "Our study revealed that CDK5 expression levels were higher in glioblastoma than in LGG." (PMID 34093802, 2021).
glioblastoma (continued). "Few recent studies convincingly demonstrate oncogenic functions for CDK5 in glioblastoma as well." (PMID 33924599, 2021). "Importantly, however, our discovery that DYRK1A attenuates CDK5 activity is important for the translation of DYRK1A inhibitors into glioblastoma therapy." (PMID 33924599, 2021). "The quinazolinone derivatives described in this study are the first small molecules reported to target CDK5 at a site other than the ATP pocket, thereby constituting attractive leads for glioblastoma therapeutics and providing therapeutic perspectives for neurodegenerative diseases." (PMID 32974274, 2020). "CDK5 is known to drive glioblastoma tumorigenicity but the downstream molecular mechanism is unknown." (PMID 31488827, 2019). "At the same time, CDK5R1 is a neural specific activator of CDK5, which could regulate glioblastoma cell migration and invasion." (PMID 27153061, 2016). "Inhibitor studies were conducted using selective inhibitors of Cdk5 and GSK3β to understand their contributions to CRMP-2 modulation, enabling the evaluation of how changes in CRMP-2 phosphorylation affected glioblastoma cell proliferation and migration." (PMID 40283503, 2025). "To validate the DYRK1A-CDK5-SOX2 axis in glioblastoma cells, we analysed how DYRK1A inhibition changes SOX2 expression in CDK5-depleted cells." (PMID 33924599, 2021). "In glioblastoma (GBM), CDK5 can amplify EGFR signaling by phosphorylating CRMP2 (collapsin response mediator protein 2) at Ser522, sustaining the pro-proliferation effect on tumor cells." (PMID 35006426, 2021). "However, CDK5 expression was significantly higher in glioblastoma than in LGG (II-III or I-III), indicating that CDK5 played an important role in disease progression." (PMID 34093802, 2021). "In glioblastoma, CDK5 over-expression segregates within mesenchymal patient clusters, indicating dependence of non-mesenchymal tumours on CDK5 activity." (PMID 33924599, 2021). "Liu and colleagues showed that CDK5 directly phosphorylated PIKE-A in its GTPase domain on glioblastoma cells, leading to the activation of its downstream effector Akt that mediated migration and invasion of human glioblastoma." (PMID 32708903, 2020). "CDK5 has also been found to phosphorylate dynamin-related protein 1 (DRP1), thereby stimulating its activity in brain tumor-initiating cells; DRP1 activation correlates with poor prognosis in glioblastoma." (PMID 32974274, 2020). "Increased expression of CDK5, p35 or p39 and the resulting hyper-activation of CDK5 have been reported in pancreatic, medullary thyroid, non-small cell lung, small cell lung, colorectal, liver, breast and ovarian cancers, glioblastoma multiforme, multiple myeloma and mantle cell lymphoma." (PMID 31910742, 2020). "Indeed, CDK5-mediated phosphorylation of phosphatidylinositol 3-kinase enhancer PIKE-A stimulates its GTPase activity, in turn activating nuclear Akt, and mediating growth factor-induced migration and invasion of glioblastoma cells." (PMID 32974274, 2020).
pancreatic cancer (22 papers, 2012 to 2024). "Using KRAS2 mutants, they reported that the loss of RalA function inhibits the tumorigenicity of pancreatic cancer cells, which is dependent on CDK5." (PMID 37993880, 2023). "Although, the role of CDK5 in the central system is well characterized, it has been recently associated with the development and progression of multiple cancers, including brain, breast, lung, colon, and pancreatic cancer." (PMID 33960694, 2021). "Through co-immunoprecipitation (Co-IP), we found evidence of a protein interaction between CCNI2 and CDK5/6 in pancreatic cancer cells." (PMID 37540586, 2024). "This study demonstrates that knockdown/overexpression of CCNI2 in pancreatic cancer cells can downregulate/upregulate the expression of CDK5 and CDK6." (PMID 37540586, 2024). "Nevertheless, as many studies have emphatically shown that CDK5 is critical for pancreatic cancer progression, the clinical significance of CDK5-mediated EZH2 degradation needs to be explored further." (PMID 37993880, 2023). "As EZH2 degradation inhibits tumor migration and invasion, CDK5 acts as a tumor suppressor in pancreatic cancer." (PMID 37993880, 2023). "In pancreatic cancer, active CDK5 phosphorylates enhancer of zeste homolog 2 (EZH2), which triggers its degradation via FBW7, a component of ubiquitin ligase." (PMID 37993880, 2023). "CDK5 activates tumor-suppressive pathways in pancreatic cancer via EZH2 degradation and in NSCLC by DLC1 activation." (PMID 37993880, 2023). "In pancreatic tumors, CDK5, p35 and p39 are overexpressed in more than 90%, 94%, and 75%, respectively, predominantly due to genomic amplification." (PMID 37993880, 2023). "To determine the combined effect of CDK5 and Notch1 signaling on pancreatic cancer cells, we measured the effect of blocking CDK5 and/or Notch signaling on cell proliferation and migration." (PMID 33960694, 2021). "Here, we used the inhibitors to explore the combined effect of CDK5 and Notch1 signaling on pancreatic cancer cells growth." (PMID 33960694, 2021). "Inhibition of CDK5 by ectopic expression of dominant-negative CDK5 constructs, or treatment of in vitro cultured cells with roscovitine significantly decreased the migration and invasion of pancreatic cancer cells." (PMID 31910742, 2020). "Based on these observations, they postulated that in pancreatic cancer cell lines, CDK5 operates downstream of Ras." (PMID 31910742, 2020). "Remarkably, we revealed that PES1 was phosphorylated and stabilized by CDK5 in pancreatic cancer cells." (PMID 31718704, 2019). "Further, we found that key nodes of regulation by our confirmed hits in this interaction map were known molecules that modulate survival, EMT and drug resistance in Ras mutated pancreatic cancers, such as YAP1, SIRT1, BAG3, ILK, CDK5, HDACs or GSK3β." (PMID 30325918, 2018). "For example, CDK5 promotes cell migration and invasion in pancreatic cancer cells, and inhibition of CDK5 suppresses pancreatic tumor growth and metastasis." (PMID 26509276, 2015). "In an orthotropic xenograft model of human pancreatic cancer, inhibition of CDK5 reduces tumor growth and metastasis." (PMID 26690371, 2015). "Inhibition of CDK5 activity reduces the tumorigenic and metastatic properties of pancreatic cancer cells." (PMID 26690371, 2015). "In two different studies on prostate and pancreatic cancer metastasis, inhibition of Cdk5 expression inhibited prostate and pancreatic cancer metastases in experimental models." (PMID 22489133, 2012). "Targeting PES1 with CDK5 inhibitors might help overcome cancer cell resistance to BET inhibitors in pancreatic cancer cells." (PMID 31718704, 2019). "Our data indicate that CDK5 modulated the stability of PES1 in pancreatic cancer cells." (PMID 31718704, 2019). "Feldmann et.al concluded that inhibiting CDK5 could suppress Ras-Ral signaling, blocking pancreatic cancer formation and progression." (PMID 29312535, 2017).